IL13 (interleukin 13)
Diseases named in the same sentence as IL13 in open-access papers (continued):
Sharing a sentence is not in itself a finding about the gene and the disease.
tetanus (6 papers, 2010 to 2018). A serious infectious disorder that follows wound contamination by the Gram-positive bacterium Clostridium tetani. "Infant malaria is associated with lower IFNγ, IL5 and IL13 (i.e. Th1) responses to both BCG and tetanus immunisation." (PMID 29124321, 2017). "Tetanus immunisation during pregnancy was associated with enhanced IFN-γ, IL-13 and (to some extent) IL-5 responses following tetanus immunisation of the offspring." (PMID 21040693, 2010). "An increasing number of doses of maternal tetanus immunisation during the pregnancy was associated with increased infant IFN-γ (aGMR 1.44 (1.16, 1.79)) and IL-13 (1.22 (1.01, 1.46)), and a weak increase in IL-5 (aGMR 1.19 (0.97, 1.44)) responses to TT." (PMID 21040693, 2010). "Tetanus immunisation during pregnancy was associated with higher infant responses to TT; maternal BCG scar (from past immunisation) with lower infant IL-5 and IL-13 responses to cCFP." (PMID 21040693, 2010). "Although IL-17 cytokine levels were significantly higher in wP-primed children for FHA and tetanus 1 month post-booster compared with aP-primed children, all IL-17 levels remained low, especially in relation to IFN-γ and IL-13 levels." (PMID 29416544, 2018). "The proportion of children for whom positive responses to cCFP, antigen 85 and tetanus toxoid were detected varied by cytokine: for cCFP, 86%, 48%, 71% and 90% of infants had positive responses to IFN-γ, IL-5, IL-13 and IL-10, respectively." (PMID 23236367, 2012). "It was particularly interesting to observe a high increase of IgG2 that has been described to correlate with IgG4 responses to tetanus vaccine in autoantibody negative children, and both subclasses correlated with IL-4 and IL-13 secretion." (PMID 30009185, 2018). "Of note, only maternal Mansonella perstans infection was associated with significantly higher IL10 responses to BCG and tetanus immunisation but with no reduction in IFNγ, IL5 and IL13 responses." (PMID 29124321, 2017). "For example, subjects with atopy had significantly greater IL‐13 responses to PHA (median values 934 vs. 560 pg/mL, respectively) and to antigen specific stimuli (median values: cockroach, 17 vs. 2; dust mite, 135 vs. 59; tetanus 98 vs. 53 pg/mL) as compared to nonatopic subjects." (PMID 27042305, 2016).
ZIKV infection (6 papers, 2018 to 2021). "Cytokine profiles in acute ZIKV infections were estimated using a multiplex bead analysis assay which measured interleukin (IL) 1β, IL-2, IL-4, IL-6, IL-8, IL-9, IL-10, IL-13, and IL-17." (PMID 30682026, 2019). "For example, Zika virus infection was associated with an increased secretion of IL2, IL4, IL13, and IL9 cytokines." (PMID 29937515, 2018). "We next tested whether the restricted ZIKV infection in MDMs was due to the lower expression level of DC-SIGN by treating MDMs with IL-13, which is known to upregulate DC-SIGN expression, followed by infecting the cells with ZIKV." (PMID 33979266, 2021). "We do not know whether lower levels of IL-1β, IL-6, IL-8, IL-10, IL-12, IL-13, IL-17A, TNF, and IFN-γ in ZIKV offspring at 32 days were caused by subclinical in utero ZIKV infection or maternal cytokine background." (PMID 31725819, 2019).
acute GVHD (5 papers, 2006 to 2025). "Therefore, association between IL-13 levels and acute GVHD may be exploited as a strong predictor of this disease." (PMID 28819653, 2017). "This means that our study did not have the opportunity to widen its considerations on more cytokines such as IFN-γ, G-CSF, GM-CSF, IL-2, IL-3, IL-5, and IL-13, which all have a known role in acute GVHD." (PMID 39728035, 2024). "Production of similar levels of IL13 in T cells in vitro has been shown to be prognostic for the development of acute graft-versus-host disease in patients who have received unrelated donor stem cell transplantation." (PMID 17060934, 2006). "The low levels of IL-13 align with low acute GVHD grades II-IV in home care patients." (PMID 39170616, 2024). "We found higher levels of IFN-γ, IL-2, IL-5, IL-13, GM-CSF, and G-CSF, but lower VEGF in hospital-treated patients, which may contribute to acute GVHD grades II-IV." (PMID 39170616, 2024). "In summary, it is now clear that acute GVHD is not a purely Th1-type cytokine-driven response, but Th2-type cytokine such as IL-13 has also been involved in the pathogenesis of acute GVHD." (PMID 28819653, 2017).
alopecia areata (5 papers, 2020 to 2025). Loss of scalp and body hair involving microscopically inflammatory patchy areas. "To date, genome-wide association studies identified only a few susceptibility loci for alopecia areata associated with Th cytokines such as IL-2/IL-21 and IL-13." (PMID 34943905, 2021). "Some authors described an increased serum level of IL-13 in patients with alopecia areata in comparison with the control group." (PMID 34943905, 2021). "The efficacy of anti-IL-4 receptor alpha monoclonal antibody (dupilumab), anti-IL-13 monoclonal antibody (tralokinumab), and anti-IL-6 monoclonal antibody (siltuximab) in alopecia areata is still under investigation." (PMID 34943905, 2021). "In a few studies, serum level of IL-13 in patients with alopecia areata was comparable with healthy controls; thus, further studies are needed to confirm the role of this cytokine in alopecia areata." (PMID 34943905, 2021). "In addition to Th1, cytokines such as IFN-gamma, Th2 cytokines, and especially IL-13 are also upregulated in alopecia areata." (PMID 35162962, 2022). "Smoking increases the levels of Th2 inflammatory cytokine IL-13 and enhances Th2 polarization in an ERK-dependent mechanism, suggesting that the Th2-mediated immune response in alopecia areata might be exacerbated by smoking exposure." (PMID 35162962, 2022).
anemia (5 papers, 2015 to 2024). A reduction in the number of red blood cells, the amount of hemoglobin, and/or the volume of packed red blood cells. "Of the six patients treated with 1 μg/kg IL-13-PE, the most common AEs included Grade 1 or 2 anemia, proteinuria, increase in alanine aminotransferase (ALT), aspartate aminotransferase (AST), creatinine and fatigue, all of which were seen in three patients." (PMID 25767039, 2015). "Comparisons of patients with mild TB and mod-sev disease or anemia, demonstrated that Th1 (IL-2, IFN-γ, and TNF-α) as well as Th2 (IL-4, IL-13, and IL-10) and Th17 responses were higher in mild TB disease." (PMID 38162636, 2023). "Trend analysis of IL-2, IL-5, FGF, PDGF-bb, IL-17, CCL5, IL-4, IL-13, IFN-γ, IL-7 and TGF-β1 uncovered that as the severity of anemia increased, the concentrations of these inflammatory molecules decreased." (PMID 37143662, 2023). "Other markers ranked to separate anemia from non-anemia included IL-2, IL-1 receptor antagonist (RA), IL-13, IFN-γ, RANTES (CCL5) and IP-10." (PMID 38162636, 2023).
cardiac hypertrophy (5 papers, 2021 to 2026). "Among the T-cell subpopulations, it appears that the CD4+ T-cells are the dominant immune mediators involved in the remodeling process that occurs in the postischemic myocardium and in maladaptive myocardial hypertrophy via the release of fibrosis promoting cytokines such as IL-4 and IL-13." (PMID 39273110, 2024).
chlamydial infection (5 papers, 2008 to 2023). "Collectively our findings demonstrate that innate IL-13 release promotes infection that results in enhanced inflammation and have broad implications for the treatment of chlamydial infections and IL-13-associated diseases." (PMID 21573182, 2011). "Incubation for 24 hours still allows for the formation of large inclusions within infected cells and is appropriate for analysing of the effect of IL-13 depletion on cellular susceptibility to chlamydial infection." (PMID 21573182, 2011). "Furthermore, the fact that IL-13 mediates susceptibility to genital tract infection highlights the potential widespread role of this molecule in promoting chlamydial infection and diseases." (PMID 21573182, 2011). "Increases in pulmonary IL-13 in asthmatic patients may promote susceptibility and contribute to the prevalence of chlamydial infection in these patient populations." (PMID 21573182, 2011). "CD8 T cells have conflicting roles in chlamydial infections, having been shown to cause immunopathology, predominantly through the production of TNFα, but in some cases also protection through atypical Chlamydia-specific cells secreting IL13 in addition to TNFα, IFNγ, and IL10." (PMID 36799886, 2023). "Though not significant, these neonates also presented with elevated IL-2, IL-10, and IL-13 when compared to adult mice, showing that chlamydial infection alone was enough to elicit a Th2-like response." (PMID 24376704, 2013). "In this study we have shown for the first time that IL-13 responses to Cmu infection are important in establishing and promoting chlamydial infection, and inflammation and disease in the respiratory and genital tracts." (PMID 21573182, 2011). "This study enhances our understanding of the pathogenesis of chlamydial infection and identifies IL-13 as new potential target to attenuate infection, inflammation and pathology associated with Chlamydia." (PMID 21573182, 2011). "In our study the influence of IL-13 on chlamydial infection was evident as early as 3 days p.i., again suggesting a novel role for this cytokine in the innate rather than acquired immune response to infection." (PMID 21573182, 2011). "In the present study we extend these studies and show that IL-13 promotes chlamydial infection and has an unexpected role in the immediate host defence responses to infection." (PMID 21573182, 2011). "The role of IL13 in chlamydial infections is unclear, particularly for males." (PMID 36799886, 2023). "Our results suggest that IL-13 responses enhance chlamydial infections and that this factor may be a new therapeutic target for the treatment of disease." (PMID 21573182, 2011). "Together, these observations suggest that the reduced susceptibility to chlamydial infection in the absence of IL-13 is not mediated by CD4+ T cells but is linked to the innate host defence response." (PMID 21573182, 2011). "Next we assessed the temporal expression of IL-13 during chlamydial infection." (PMID 21573182, 2011). "We also assessed the systemic response by splenic T cells expressing cytokines with known importance to resolution of chlamydial infections and pathology; IFNγ, TNFα, IL17, IL13, IL10." (PMID 36799886, 2023). "To explore the mechanisms by which IL-13 mediates the host response to Cmu lung infection, we determined whether IL-13 influences the expression of IFN-γ and IL-10, factors known to play a central role in the immune response to chlamydial infection." (PMID 21573182, 2011).
cyst (5 papers, 2012 to 2022). A sac-like closed membranous structure that may be empty or contain fluid or amorphous material. "Compared with BALB/c mice, FVB mice is a more favorable host for C. sinensis on the basis of cyst formation in bile ducts because they have increased production of Th2-associated anti-inflammatory cytokines, including IL-4, IL-5, IL-13, IL-10 and TGF-β." (PMID 28784165, 2017). "The levels of IFN-γ, IL-1β, IL-2, IL-4, IL-10, IL-12, and IL-13, in contrast, were significantly higher in pus than in cyst fluid." (PMID 35965529, 2022). "Together with the overproduction of IL-4, IL-5, and IL-13, these cytokines may mount a response that could destroy the T. saginata PO form and prevents development of the cyst in vivo." (PMID 30870421, 2019). "With the exception of the association of IL-4 and IL-13 with the cyst stage, all other cytokines did not associate with cyst stages." (PMID 25429386, 2014).
dementia (5 papers, 2014 to 2024). Loss of intellectual abilities interfering with an individual's social and occupational functions. "The current findings, in combination with many experimental results, suggest that the deleterious actions of microglia/macrophages-derived endogenous IL-4 and/or IL-13 are possibly involved in oxidative stress-mediated neurodegenerative disease, such as dementia and AD." (PMID 31010119, 2019). "In comparison to other dementias (AD or CJD), MS and controls, we observed an elevated level of proinflammatory cytokines (IL-6, IL-13, TNF-α and G-CSF) specifically in the serum of rpAD patients." (PMID 25315814, 2014). "The cytokines IL-13 and IL-1α were significantly associated with less tau pathology in APOE ε4 negative participants and were not independently predictive of dementia." (PMID 32076055, 2020).
dry eye (5 papers, 2012 to 2025). "IL-13KO mice have decreased goblet cell density at baseline and subconjunctival injections of IL-13 during experimental dry eye rescued goblet cell density compared to placebo-injected mice." (PMID 27623073, 2016). "Increases of IFN-γ, IL-2, IL-4, IL-5, IL-13 or IL-β1 in SAC; TSLP in both PAC and SAC; and IL-17, IL-21 and IL-22 in dry eyes have been observed in different studies." (PMID 35935953, 2022).
encephalitis (5 papers, 2016 to 2025). An acute inflammatory process affecting the brain parenchyma. "For example, in EV71 patients with encephalitis, IL-13 and IL-4 were the most increased cytokines, whereas in EV71 patients without encephalitis, IL-22 and macrophage inflammatory protein-1a (MIP-1a) were the most increased cytokines." (PMID 34079547, 2021).
endothelial dysfunction (5 papers, 2019 to 2025). In vascular diseases, endothelial dysfunction is a systemic pathological state of the endothelium (the inner lining of blood vessels) and can be broadly defined as an imbalance between vasodilating and vasoconstricting substances produced by (or acting on) the endothelium. "IL-4 and IL-13 are associated with cardiac fibrosis and hypertrophy, while IL-1β mediates inflammation, endothelial dysfunction and myocardial injury." (PMID 39633480, 2024). "Moreover, changes in cytokine levels, such as IL-6 (interleukin 6), IL-10 (interleukin 10), and IL-13 (interleukin 13), are associated with treatment-related toxicities, notably fatigue and endothelial dysfunction." (PMID 40136656, 2025). "Baicalein displayed anti-inflammatory effects by attenuating endothelial dysfunction and the inflammatory mediators, such as IL-33, IL-6, IL-1β, MMP-9, and IL-13, in radiation enteropathy." (PMID 31474856, 2019). "Furthermore, studies have demonstrated that 20-HETE stimulates the production of inflammatory cytokines, including IL-8, IL-13, IL-4, and PGE2, in endothelial cells resulting in endothelial cell activation and endothelial dysfunction." (PMID 36238558, 2022).
esophageal cancer (5 papers, 2020 to 2025). A primary or metastatic malignant neoplasm involving the esophagus. "Circulating IL-4 was elevated in all, while IL-13 only in colorectal or esophageal cancers, reflecting their advancement." (PMID 32512917, 2020). "We also showed distinct systemic cytokine signatures in gastric and esophageal cancers and their benign conditions, with cytokine panels consisting of IL-1β/IL-1ra/IL-6/RANTES or IL-1β/IL-6/IL-4/IL-13 holding promise as differential biomarkers in GC." (PMID 32630408, 2020).
gingivitis (5 papers, 2021 to 2025). A disorder involving inflammation of the gums; may affect surrounding and supporting structures of the teeth. "In experimental gingivitis, IL-13 was one of the cytokines associated with gingival inflammation and its fast development." (PMID 36791096, 2023). "In patients with gingivitis, levels of IL-1β, IL-6, IL-7, IL-13, IL-17, IL-21 and MIP-3α in gingival crevicular fluid in the Sg group were lower in comparison with the Dg group." (PMID 33417619, 2021). "The biomarker IL-13 was below the detection limit in the healthy and gingivitis groups." (PMID 33806927, 2021). "IL-1β, IL-6, IL-7, IL-13, IL-17, IL-21 and MIP-3α in GCF of T2DM patients with gingivitis were significantly downregulated by statins treatment." (PMID 33417619, 2021). "In subjects with gingivitis, compared with the Cg group, levels of inflammatory factors IFN-γ, IL-4, IL-5, IL-6, IL-10 and IL-13 were significantly lower in saliva in the Dg group (p<0.05)." (PMID 33417619, 2021).
heart failure (5 papers, 2018 to 2022). Inability of the heart to pump blood at an adequate rate to meet tissue metabolic requirements. "Pro-inflammatory cytokines, such as IL-1β, IL-6 and IL-13, play a significant role in regulating the progression from adaptive hypertrophy to heart failure." (PMID 31333486, 2019). "Similarly, a very recent study demonstrated that IL-13 gene expression tended to increase in the left ventricular free wall of T2D patients with heart failure as compared to healthy donors." (PMID 29675435, 2018). "Interestingly, despite IL-13 gene tended to be upregulated, the IL-13 receptor subunit alpha 1 (IL-13Rα1) production was significantly decreased in the same cardiac muscle specimens of T2D patients with heart failure, who are by definition insulin-resistant." (PMID 29675435, 2018).
Hypercholesterolemia (5 papers, 2008 to 2024). An increased concentration of cholesterol in the blood.
ileitis (5 papers, 2011 to 2023). "Moreover, mice with high expression of TLIA can develop spontaneous ileitis, proximal colitis, and even fibrosis, which is associated with elevated levels of fibrotic factor interleukin-13 (IL-13)." (PMID 34257516, 2021). "Expression of IL-13 was increased in TL1A transgenic mice, and blocking IL-13 release alleviates the severity of ileitis." (PMID 34257516, 2021). "Indeed, TL1A-Tg mice displayed elevations in mucosal IL-13 and IL-5 mRNA content, whereas, blockade of IL-13 ameliorated the severity of ileitis." (PMID 30972074, 2019). "However, a major difference was that the ileitis found in the recently published Tl1a Tg mice appeared to be mainly attributed to Th2/IL-13 effector pathway, whereas we observed a higher production of IFN-γ from the Tl1a Tg mice generated in this study." (PMID 21264313, 2011).
lung adenocarcinoma (5 papers, 2015 to 2025). A carcinoma that arises from the lung and is characterized by the presence of malignant glandular epithelial cells. "Our study uniquely identified IL-1RA as a potential risk factor for lung adenocarcinoma and revealed that MCP-1, IL-10, IL-13, and TRAIL were significant factors for lung squamous cell carcinoma." (PMID 39132165, 2024). "The importance of Th2 cytokines, including IL-4, IL-10, and IL-13, in the regulation of the protumor functions of TAMs has also been demonstrated in human lung adenocarcinomas." (PMID 26242181, 2015). "Basophils co-cultured with human lung adenocarcinoma A549 released IL-4 and IL-13." (PMID 40873585, 2025). "Furthermore, the regulation of the necroptosis pathway, which is closely associated with the inflammatory environment induced by IL-4/IL-13, may be involved in PLK1-mediated modulation of the immune microenvironment in lung adenocarcinoma (LA) patients." (PMID 37744268, 2023).
malnutrition (5 papers, 2020 to 2022). Inadequate nutrition resulting from poor diet, malabsorption, or abnormal nutrient distribution. "This change in tissue resident ILC frequencies in response to malnutrition increases both the susceptibility of mice to bacterial infections and the protection against helminth infection due to the elevated levels of IL-13." (PMID 32079296, 2020). "Malnutrition promotes the phenotypic transformation of immune cells to pro-inflammatory phenotypes, secreting pro-inflammatory cytokines such as IL-1β, IL-6, IL-8, TNF-α, and IL-2, while anti-inflammatory cytokines such as IL-1 receptor antagonists, IL-4, IL-10, and IL-13 decrease." (PMID 35003070, 2021). "Malnutrition does not result in the elevation of other ILC2-derived cytokines, likely due to the essential nature of IL-13 for barrier protection." (PMID 32079296, 2020).